UBE2D1 (ubiquitin conjugating enzyme E2 D1)
Diseases named in the same sentence as UBE2D1 in open-access papers:
UBE2D1 is named in the same sentence as 49 diseases in open-access papers, as found by Europe PMC text mining. Sharing a sentence is not in itself a finding about the gene and the disease. The quoted sentences say what the papers report.
hepatocellular carcinoma (7 papers, 2018 to 2025). A malignant tumor that arises from hepatocytes. "Previous studies reported that upregulated UBE2D1 is found in several cancers including non-small-cell lung cancer, osteosarcoma, and hepatocellular carcinoma." (PMID 34743754, 2021). "DLST SLC31A1, LIPT1, and UBE2D1 are reported to regulate cuproptosis in sepsis, hepatocellular carcinoma, multiple myeloma, thyroid carcinoma, oral squamous cell carcinoma, rheumatoid arthritis, periodontitis, gastric cancer, colorectal cancer, and myocardial infarction." (PMID 40980812, 2025). "UBE2D1, previously shown to be upregulated by VPA in SH-SY5Y neuronal cells and associated with hepatocellular carcinoma progression, was similarly elevated in VPA monotherapy and reversed with FA, suggesting FA may counteract such adverse proliferative effects." (PMID 40869302, 2025).
gastric cancer (5 papers, 2021 to 2025). A primary or metastatic malignant neoplasm involving the stomach. "Recently, UBE2D1 has been indicated to be a potential biomarker for the therapy of gastric cancer." (PMID 34743754, 2021). "In addition, Li and his team showed that lncRNA HCG11 could reverse the chemotherapy resistance of stomach cancer via the miR-144-3p/UBE2D1 pathway." (PMID 35342421, 2022). "UBE2D1 might be a potential target for gene therapy for human gastric cancer." (PMID 34743754, 2021).
diabetes (4 papers, 2019 to 2025). "Diabetes is a known risk factor for CKD, hence, further supporting the candidacy of UBE2D1 for a CKD target as deduced herein." (PMID 37123453, 2023). "Similar to these studies, our investigation of co-expressed genes, aimed at gaining a better understanding of the relationship between diabetes and sepsis, revealed UBE2D1 and COX7C as potential biomarkers and therapeutic targets for DRS." (PMID 35445133, 2022). "UBE2D1 has been identified as a potential biomarker for diabetes-related sepsis." (PMID 38779731, 2025). "We report associations of CAD with the PLXDC2 gene and DR with the UBE2D1 gene, both of these genes may contribute to DR and CAD as part of diabetes progression by playing a role in angiogenesis and neovascularization." (PMID 31130920, 2019). "UBE2D1, a CKD candidate, is inferred as a potential biomarker for diabetes-related sepsis by a machine-learning pipeline using public databases." (PMID 37123453, 2023).
lung adenocarcinoma (4 papers, 2018 to 2025). A carcinoma that arises from the lung and is characterized by the presence of malignant glandular epithelial cells. "UBE2D1, a gene linked to cuproptosis, serves as a prognostic indicator in lung adenocarcinoma and participates in shaping the immune microenvironment." (PMID 41208974, 2025). "Overexpression of UBE2D1 has been shown to be associated with poor prognosis in several human cancers, such as breast cancer, liver cancer, bladder cancer and lung adenocarcinoma." (PMID 39353886, 2024). "The study showed that UBE2D1 significantly upregulated in lung adenocarcinoma (LUAD) and lung squamous cell carcinoma (LUSC), and it served as an independent prognostic indicator of unfavorable OS and RFS in LUAD." (PMID 34946806, 2021). "Results showed that both lung adenocarcinoma (LUAD) (N = 514) and lung squamous cell carcinoma (LUSC) (N = 502) tissues had significantly elevated UBE2D1 RNA expression compared to the normal tissues (p < 0.001 and p = 0.036, respectively)." (PMID 30420903, 2018).
Sepsis (4 papers, 2022 to 2025). Sepsis is defined as life-threatening organ dysfunction caused by a dysregulated host response to infection. "The expression of SLC31A1, CD274, ATOX1, MTF1, UBE2D1, DLD, and VEGFA was found to be upregulated, while that of DLST, UBE2D2, COX11, DLAT, GLS, FDX1, and ULK2 were significantly downregulated in patients with sepsis-associated ALI." (PMID 38779731, 2025).
colorectal cancer (3 papers, 2018 to 2025). A primary or metastatic malignant neoplasm that affects the colon or rectum. "One of its interacted genes, UBE2D1, a member of ubiquitin-conjugating enzyme E2D family, related to the Aurora kinase A (AURKA), which was an enhancer of Wnt and Ras-MAPK signaling in colorectal cancer (CRC)." (PMID 34946806, 2021). "Recently, UBE2D1 was reported to connect the overexpression of Aurora kinase A with Wnt and Ras-MAPK signaling pathways in colorectal cancer, suggesting UBE2D1 may play an important role in the progression from adenoma-to-carcinoma." (PMID 30482241, 2018).
Hepatitis (2 papers, 2018 to 2024). Inflammation of the liver. "Additionally, the HCC tissues had a higher genomic level of UBE2D1 than normal liver tissues or hepatitis liver tissues, corresponding to the transcript level." (PMID 30482241, 2018). "In addition, UBE2D1 had also been found to be overexpressed in precancerous lesions, and it was only upregulated in cancer cells rather than hepatitis cells, suggesting its potential as an early-stage HCC marker." (PMID 39353886, 2024). "Moreover, UBE2D1 was also overexpressed in precancerous lesions and was upregulated only in cancer cells but not in hepatitis cells, indicating UBE2D1 as a specific HCC marker in early stage." (PMID 30482241, 2018). "Immunohistochemistry (IHC), western blotting, and real-time PCR were used to detect the protein, transcription and genomic levels of UBE2D1 in HCC tissues with paired nontumor tissues, precancerous lesions and hepatitis liver tissues." (PMID 30482241, 2018). "More importantly, the genome content of UBE2D1 was also higher in precancerous lesions and HCC tissues but not in hepatitis tissues, suggesting that genomic alteration of UBE2D1 may play an important role in carcinogenesis of HCC." (PMID 30482241, 2018).
Arthritis (1 paper, 2025). Inflammation of a joint. "To validate these observations in vivo, we used Ube2d1 knockout mice, which exhibit impaired CXCL10 induction and attenuated arthritis severity, highlighting the pivotal role of Ube2d1 in driving this inflammatory program." (PMID 42004226, 2025).
atherosclerosis (1 paper, 2023). A disease characterized by the build-up of fatty material and calcium deposition in the arterial wall resulting in partial or complete occlusion of the arterial lumen. "In the training dataset GSE97210, SLC31A1, ATP7A, SLC31A2, UBE2D1, CP and FDX1 were highly expressed while LOXL2, COA6 and SOD1 were lowly expressed in the atherosclerosis group as showed in the bar charts." (PMID 37324184, 2023).
autoimmune disease (1 paper, 2021). A disorder resulting from loss of function or tissue destruction of an organ or multiple organs, arising from humoral or cellular immune responses of the individual to their own tissue constituents. "The majority of reported nominally significant associations overlap with previously reported susceptibility loci for RA; overlaps with other autoimmune diseases were observed for UBE2D1 associated with Crohn’s disease, PRDM1 with systemic sclerosis, and VAV1 with multiple sclerosis." (PMID 34101054, 2021).
depression (1 paper, 2022). "In this research, UBE2W and UBE2D1 were detected to be down-regulated in MDD adolescents, indicating down-regulation the in immune function of major depression." (PMID 35328018, 2022). "Although previous studies have not identified UBE2W and UBE2D1 to be closely correlated with depression, transcriptome analyses have discovered that depression is linked to a range of biological processes which may be involved in inflammation and immune activation." (PMID 35328018, 2022).
osteoporosis (1 paper, 2025). A condition of reduced bone mass, with decreased cortical thickness and a decrease in the number and size of the trabeculae of cancellous bone (but normal chemical composition), resulting in increased fracture incidence. "It showed that in osteoporosis patients, CP (P < 0.01), LIPT1 (P < 0.05), SLC25A3 (P < 0.001), and UBE2D3 (P < 0.01) were upregulated, while the expression levels of CDKN2A (P < 0.05), DBH (P < 0.01), DLST (P < 0.05), LOXL2 (P < 0.05), SLC31A1 (P < 0.05), and UBE2D1 (P < 0.01) were downregulated." (PMID 40980812, 2025).
renal carcinoma (1 paper, 2025). A carcinoma arising from the epithelium of the renal parenchyma or the renal pelvis. "MKRN2, ZNF598, UBE2D1, and TRIM25 were potential factors influencing renal cancer progression." (PMID 40959281, 2025).
viral infection (1 paper, 2017). "We noticed that on viral infection, Ube2D1/2/4−/− and Ube2N/E1−/− cells produced more IFN than Ube2N−/− cells, which could be due to the negative effect of those E2s on IFN-β." (PMID 28469175, 2017).
tumor (14 papers, 2018 to 2026). "The results indicated that elevated levels of UBE2D1 expression in tumor tissues were significantly linked to decreased overall survival rates in HCC patients." (PMID 39353886, 2024). "IDH1 mutation in CT26 tumor-bearing mice resulted in increased expression of Ube2d1, Trim63, and Fbxo32, while ivosidenib treatment inhibited the upregulation of UPP-related enzymes." (PMID 37741882, 2023). "As shown, tumor volume and tumor weight were significantly reduced in both the sh-UBE2D1 group and control + cDDP group compared to the control group." (PMID 39353886, 2024). "To determine the significance of UBE2D1 in GC, we analyzed the expression level of UBE2D1 in TCGA-STAD and found that UBE2D1 was upregulated in primary tumor (n = 415) compared to the normal tissue (n = 14)." (PMID 34743754, 2021). "Ubiquitin-conjugating enzyme E2 D1 (UBE2D1), a key component of the ubiquitination machinery, has been implicated in tumor progression in several cancers; however, its relevance in HNSCC remains unclear." (PMID 41732664, 2026). "Notably, the tumor volume and weight of the shUBE2D1 + cDDP group were the lowest among all groups, indicating that UBE2D1 knockdown enhanced the inhibitory effect of cDDP on tumor growth." (PMID 39353886, 2024). "Then we examined the UBE2D1 expression in the precancerous lesions and paired adjacent tissues without lesions to find that precancerous lesions had a higher UBE2D1 level than adjacent normal tissues, indicating the pro-tumor role of UBE2D1 at the early stage of HCC." (PMID 30482241, 2018). "Similarly, UBE2D1 level was higher in the tumor tissues than the paracancerous tissues." (PMID 34743754, 2021). "We found that UBE2D1 could promote the tumor growth in vivo." (PMID 30482241, 2018). "Specifically, PIWIL4, SATB1, GSE1, NCOR1, SAP30L, ATM, and BMI1 were significantly downregulated in tumor tissues relative to normal controls, while BUB1, CHEK1, MASTL, DNAJC2, UBE2D1, and SSRP1 showed pronounced upregulation." (PMID 41208974, 2025). "High expression of UBE2D1 and UBE2D3 can promote the proliferation, invasion and metastasis of tumor cells, and inhibit the apoptosis of tumor cells." (PMID 37886979, 2023). "To further explore whether UBE2D1 expression level was associated with the clinical outcome of HCC patients, we performed Kaplan-Meier analysis to reveal that the high expression level of UBE2D1 in tumor tissues was correlated with reduced overall survival of the HCC patients in GSE14520." (PMID 30482241, 2018). "As indicated by UALCAN database, the mRNA expression levels of HLA-A, TMEM129, UBE2D1, UBE2N, UBE2T in BCa tissue were significantly increased compared with that in normal tissue; however, the mRNA expression level of USP5 was similar between normal and tumor tissue." (PMID 34776794, 2021).
cancer (12 papers, 2013 to 2026). A tumor composed of atypical neoplastic, often pleomorphic cells that invade other tissues. "The ubiquitin-conjugating enzyme E2D1 (UBE2D1), a member of the E2 family, is involved in various cancer-related signaling pathways through its ubiquitination modification mechanism." (PMID 39353886, 2024). "Using IHC staining data in the HPA, we also assessed UBE2D1 expression at the protein level in cancer tissues and normal lung tissues." (PMID 30420903, 2018). "Knockdown of UBE2D1 impairs cancer cell migration by reducing SMAD4 ubiquitination." (PMID 41208974, 2025). "Researchers suggest that UBE2D1 may exhibit great importance in the regulation of cancer-related signaling pathways." (PMID 34743754, 2021). "As copy number variations is the crucial event early in hepatocarcinogenesis, and controls the gene expression to initiate cancers, we investigated whether the upregulation of UBE2D1 in HCC was attributed to copy number variations." (PMID 30482241, 2018). "However, the biological functions of UBE2D1 in cancers were unclear." (PMID 30482241, 2018). "Our findings showed that UBE2D1 played a crucial role in HCC progression, and suggested a novel pattern of continuous IL-6 to promote cancers by inducing the genomic alterations of specific oncogenes." (PMID 30482241, 2018). "Among them, we again identified three cancer-related genes (NEK7, UBE2D1 and FLRT3), whose mRNA expressions were repressed by miR-101 overexpression in SPAC-1-L cells and induced by AS-101 in HOUA-I cells." (PMID 25153722, 2014). "Therefore, LOXL2, UBE2D1, UBE2D3, and DβH can be considered as potential candidates for cancer diagnosis, prognosis, and therapeutic biomarkers." (PMID 37886979, 2023). "Structural analysis of CNPY2 interaction with UBE2D1 is required to improve our understanding of how CNPY2 inhibits MYLIP-UBE2D1 interaction, which may lead to development of new targeted therapy for cancer." (PMID 29707137, 2018).
infection (2 papers, 2013 to 2023). The state of being infected such as from the introduction of a foreign agent such as serum, vaccine, antigenic substance or organism. "Depletion of UBE2D1-4, UBE2E1-3 and UBE2N significantly increased the number of PML-positive cells post-infection, in an ICP0-dependent manner, indicating that ICP0 can use multiple E2s to degrade PML." (PMID 23950709, 2013). "In vitro, ICP0 is a biochemically active E3 ubiquitin ligase in the presence of E2 ubiquitin conjugating enzymes (E2s) [UBE2D1 (UbcH5a) and UBE2E1 (UbcH6)], but which E2s are used during infection has remained unclear." (PMID 23950709, 2013).
neurodegenerative disease (1 paper, 2021). A disorder of the central nervous system characterized by gradual and progressive loss of neural tissue and neurologic function. "Several interacting proteins are known to be the pathological hallmarks of neurodegenerative diseases, such as tau protein encoded by MAPT, α-synuclein encoded by SNCA, and ubiquitin conjugating enzyme E2 D1 (UBE2D1)." (PMID 34565360, 2021).
retinopathy (1 paper, 2019). "A protein-coding gene, UBE2D1 (ubiquitin conjugating enzyme E2 D1), located near rs4462262 was previously investigated for function and possible involvement in the development of retinopathy." (PMID 31130920, 2019).
UBE2D1 also shares sentences with these, for which no sentence is quoted: breast carcinoma (3 papers); bladder cancer (2); leukemia (2); liver cancer (2); Lung Squamous Cell Carcinoma (2); osteosarcoma (2); acute lymphoblastic leukemia (1); adenoma (1); chronic fatigue syndrome (1); Crohn disease (1); diabetic retinopathy (1); glioblastoma (1); head and neck cancer (1); head and neck squamous cell carcinoma (1); hematological malignancies (1); iron deficiency (1); Kawasaki disease (1); lymphoma (1); melanoma (1); multiple myeloma (1); multiple sclerosis (1); myocardial infarction (1); non-small cell lung carcinoma (1); Obesity (1); oral squamous cell carcinoma (1); periodontitis (1); rheumatoid arthritis (1); stomach cancer (1); systemic sclerosis (1); thyroid carcinoma (1).